ZNHIT1 (zinc finger HIT-type containing 1)
Description:
Plays a role in chromatin remodeling by promoting the incorporation of histone variant H2AZ1/H2A.Z into the genome to regulate gene expression. Promotes SRCAP complex-mediated deposition of histone variant H2AZ1 to lymphoid fate regulator genes, enhancing lymphoid lineage commitment (By similarity). Recruited to the promoter of the transcriptional activator MYOG at the early stages of muscle differentiation where it mediates binding of histone H2AZ1 to chromatin and induces muscle-specific gene expression. Maintains hematopoietic stem cell (HSC) quiescence by determining the chromatin accessibility at distal enhancers of HSC quiescence genes such as PTEN, FSTL1 and KLF4, enhancing deposition of H2AZ1 to promote their sustained transcription and restricting PI3K-AKT signaling inhibition (By similarity). Plays a role in intestinal stem cell maintenance by promoting H2AZ1 deposition at the transcription start sites of genes involved in intestinal stem cell fate determination including LGR5, TGFB1 and TGFBR2, thereby contributing to gene transcription (By similarity). Promotes phosphorylation of the H2AZ1 chaperone VPS72/YL1 which enhances the interaction between HZAZ1 and VPS72 (By similarity). Regulates the entry of male germ cells into meiosis by controlling histone H2AZ1 deposition which facilitates the expression of meiotic genes such as MEIOSIN, leading to the initiation of meiosis (By similarity). Required for postnatal heart function through its role in maintenance of cardiac Ca(2+) homeostasis by modulating the expression of Ca(2+)-regulating proteins CASQ1 and ATP2A2/SERCA2A via deposition of histone H2AZ1 at their promoters (By similarity). During embryonic heart development, required for mitochondrial maturation and oxidative metabolism by functioning through H2AZ1 deposition to activate transcription of metabolic genes and is also required to maintain the stability of the respiratory complex (By similarity). In neural cells, increases deposition of the H2AZ1 histone variant and promotes neurite growth. Recruited to the promoter of cyclin-dependent kinase CDK6 and inhibits its transcription, possibly by decreasing the acetylation level of histone H4, leading to cell cycle arrest at the G1 phase (By similarity). Plays a role in lens fiber cell differentiation by regulating the expression of cell cycle regulator CDKN1A/p21Cip1 (By similarity). Binds to transcriptional repressor NR1D2 and relieves it of its inhibitory effect on the transcription of apolipoprotein APOC3 without affecting its DNA-binding activity.
Synonyms: ZNFN4A1; CG1I; H_DJ0747G18.14; p18(Hamlet)
Tractability: Small molecule: a structure with a bound ligand is known. PROTAC: ubiquitination databases record sites on it.
Gene: Protein-coding gene on chromosome 7 (101,218,161 to 101,224,190, forward strand). Ensembl gene ENSG00000106400.
Subcellular location: Nucleus
Subcellular location (Human Protein Atlas): Nucleoplasm
Gene Ontology:
Molecular function: histone binding; protein binding; nucleosome binding; chromatin binding; histone deacetylase binding
Biological process: muscle cell differentiation; calcium ion homeostasis; chromatin remodeling; heart process; intestinal stem cell homeostasis; positive regulation of lymphoid progenitor cell differentiation; positive regulation of transcription initiation by RNA polymerase II; regulation of DNA-templated transcription; hematopoietic stem cell homeostasis; transcription initiation-coupled chromatin remodeling
Cellular component: nucleus; nucleosome
Genetic constraint (gnomAD): Loss-of-function variants: 20 observed, 22.4 expected, observed/expected ratio (o/e) 0.89, 90% interval 0.63 to 1.3. The upper end of that interval is the gene's LOEUF score, 1.3, which puts it in group 5 of 6, group 1 being the genes least tolerant of losing a copy. Missense variants: 170 observed, 222.86 expected, observed/expected ratio (o/e) 0.76, 90% interval 0.67 to 0.87. Synonymous variants: 79 observed, 87.89 expected, observed/expected ratio (o/e) 0.9, 90% interval 0.75 to 1.08.
Homologues: Orthologues: chimpanzee ZNHIT1 (100% identical), dog ZNHIT1 (100% identical), macaque ZNHIT1 (100% identical), pig ZNHIT1 (100% identical), guinea pig ZNHIT1 (99% identical), rabbit ZNHIT1 (99% identical), mouse Znhit1 (97% identical), rat Znhit1 (94% identical), tropical clawed frog znhit1 (82% identical), zebrafish znhit1 (80% identical), Drosophila melanogaster CG31917 (53% identical), Caenorhabditis elegans zhit-1 (42% identical).
Diseases named in the same sentence as ZNHIT1 in open-access papers:
ZNHIT1 is named in the same sentence as 12 diseases in open-access papers, as found by Europe PMC text mining. Sharing a sentence is not in itself a finding about the gene and the disease. The quoted sentences say what the papers report.
uterine fibroids (2 papers, 2023 to 2024). "It has been proved that patients with germinal mutation in the SRCAP members YEATS4 and ZNHIT1 predispose to uterine leiomyoma." (PMID 37466765, 2024).
Arrhythmia (1 paper, 2022). Any cardiac rhythm other than the normal sinus rhythm. "Taken together, these studies demonstrated that Znhit1 deficiency resulted in rapid heart failure and arrhythmia, leading to premature sudden death in mice." (PMID 35167494, 2022). "We generated cardiomyocyte-specific Znhit1-deletion mice, which developed arrhythmia, idiopathic vacuolar cardiomyopathy, and rapid heart failure leading to premature sudden death." (PMID 35167494, 2022). "Deletion of Znhit1 in postnatal hearts of mice resulted in arrhythmia, idiopathic vacuolar cardiomyopathy, rapid heart failure, and premature sudden death." (PMID 35167494, 2022).
breast carcinoma (1 paper, 2022). "The aim of this study was to investigate Znhit1 and HIF-2α gene expression in breast cancer tissues as well as their relation to CSCs markers LGR5, ALDH1A1 and β-catenin in tissue and serum of BC patients." (PMID 35978075, 2022).
cardiomyopathy (1 paper, 2022). A disease of the heart muscle or myocardium proper. "Collectively, these results indicate that loss of Znhit1 in the postnatal heart causes pathological cardiomyopathy leading to premature sudden death." (PMID 35167494, 2022).
heart failure (1 paper, 2022). Inability of the heart to pump blood at an adequate rate to meet tissue metabolic requirements. "These Echo results revealed a rapid heart failure in Znhit1 cKO mice." (PMID 35167494, 2022).
Splenomegaly (1 paper, 2020). Abnormal increased size of the spleen. "Besides, hematopoietic Znhit1 deficiency resulted in splenomegaly and disorganized splenic structure, which associated with myeloid cells infiltration and myeloperoxidase (MPO)-positive cells increase." (PMID 32694618, 2020).
α-synucleinopathy (1 paper, 2022). "We next sought to investigate the potential functional role of ZNHIT1 in a cellular model of α-synucleinopathy; we used human SH-SY5Y cells, which are widely used to study molecular and cellular mechanisms of relevance to PD." (PMID 35175558, 2022).
cancer (2 papers, 2022 to 2023). A tumor composed of atypical neoplastic, often pleomorphic cells that invade other tissues. "However, the function of Znhit1 in cancer remains largely unknown." (PMID 35978075, 2022).
tumor (2 papers, 2022 to 2025). "Additionally, in paired tissue samples, we observed that except for ZNHIT1, the other three genes were highly expressed in tumor tissues." (PMID 40539074, 2025). "From our study we can conclude that Znhit1 repression may play a role in tumour progression as well as induction and maintenance of stemness in BC." (PMID 35978075, 2022). "Moreover, our results revealed statistically significant negative correlation between gene expression of Znhit1 in BC tissues and clinical stage of patients, suggesting the role of Znhit1 repression in tumor progression." (PMID 35978075, 2022).
ZNHIT1 also shares sentences with these, for which no sentence is quoted: acute myeloid leukemia (2 papers); dilated cardiomyopathy (1); Uterine leiomyoma (1).